SPTLC1 (serine palmitoyltransferase long chain base subunit 1)
Description:
Component of the serine palmitoyltransferase multisubunit enzyme (SPT) that catalyzes the initial and rate-limiting step in sphingolipid biosynthesis by condensing L-serine and activated acyl-CoA (most commonly palmitoyl-CoA) to form long-chain bases. The SPT complex is also composed of SPTLC2 or SPTLC3 and SPTSSA or SPTSSB. Within this complex, the heterodimer with SPTLC2 or SPTLC3 forms the catalytic core. The composition of the serine palmitoyltransferase (SPT) complex determines the substrate preference. The SPTLC1-SPTLC2-SPTSSA complex shows a strong preference for C16-CoA substrate, while the SPTLC1-SPTLC3-SPTSSA isozyme uses both C14-CoA and C16-CoA as substrates, with a slight preference for C14-CoA. The SPTLC1-SPTLC2-SPTSSB complex shows a strong preference for C18-CoA substrate, while the SPTLC1-SPTLC3-SPTSSB isozyme displays an ability to use a broader range of acyl-CoAs, without apparent preference. Required for adipocyte cell viability and metabolic homeostasis (By similarity).
Synonyms: SPT1; LCB1; SPTI; HSAN1; hLCB1; ALS27; HSN1; LBC1
Tractability: Small molecule: a structure with a bound ligand is known; a high-quality ligand is known. Antibody: UniProt predicts a signal peptide or a membrane-spanning region. PROTAC: ubiquitination databases record sites on it; its protein half-life has been measured; a small molecule that binds it is known.
Target class: Enzyme; Transferase
Gene: Protein-coding gene on chromosome 9 (92,000,087 to 92,115,433, reverse strand). Ensembl gene ENSG00000090054.
Subcellular location: Endoplasmic reticulum membrane
Subcellular location (Human Protein Atlas): Endoplasmic reticulum
Pathways (Reactome):
Metabolism: Sphingolipid de novo biosynthesis
Gene Ontology:
Molecular function: protein binding; serine C-palmitoyltransferase activity; pyridoxal phosphate binding
Biological process: ceramide biosynthetic process; glycosphingolipid biosynthetic process; positive regulation of lipophagy; sphingolipid biosynthetic process; sphingomyelin biosynthetic process; sphingosine biosynthetic process; regulation of fat cell apoptotic process; sphingolipid metabolic process
Cellular component: cytoplasmic side of endoplasmic reticulum membrane; endoplasmic reticulum; endoplasmic reticulum membrane; serine palmitoyltransferase complex
Genetic constraint (gnomAD): Loss-of-function variants: 36 observed, 44.53 expected, observed/expected ratio (o/e) 0.81, 90% interval 0.62 to 1.07. The upper end of that interval is the gene's LOEUF score, 1.07, which puts it in group 4 of 6, group 1 being the genes least tolerant of losing a copy. Missense variants: 388 observed, 491.35 expected, observed/expected ratio (o/e) 0.79, 90% interval 0.73 to 0.86. Synonymous variants: 165 observed, 173.59 expected, observed/expected ratio (o/e) 0.95, 90% interval 0.84 to 1.08.
Gene-disease validity (ClinGen):
ClinGen rates the evidence that SPTLC1 causes each of these diseases.
neuropathy, hereditary sensory and autonomic, type 1A (autosomal dominant): Definitive. An axonal form of hereditary motor and sensory neuropathy distinguished by prominent early sensory loss and later positive sensory phenomena, caused by mutations in SPTLC1.
Homologues: Orthologues: macaque SPTLC1 (99% identical), pig SPTLC1 (94% identical), chimpanzee SPTLC1 (93% identical), guinea pig SPTLC1 (92% identical), mouse Sptlc1 (92% identical), rat Sptlc1 (91% identical), rabbit SPTLC1 (87% identical), tropical clawed frog sptlc1 (85% identical), zebrafish sptlc1 (84% identical), dog SPTLC1 (83% identical), Drosophila melanogaster Spt-I (50% identical), Caenorhabditis elegans sptl-1 (48% identical). Paralogues in human: SPTLC2 (28% identical), SPTLC3 (27% identical), ALAS1 (23% identical), GCAT (21% identical), ALAS2 (20% identical).
Diseases named in the same sentence as SPTLC1 in open-access papers:
SPTLC1 is named in the same sentence as 72 diseases in open-access papers, as found by Europe PMC text mining. Sharing a sentence is not in itself a finding about the gene and the disease. The quoted sentences say what the papers report.
hereditary sensory and autonomic neuropathy type 1 (28 papers, 2012 to 2024). Hereditary sensory neuropathy type I (HSN I) is a slowly progressive neurological disorder characterized by prominent predominantly distal sensory loss, autonomic disturbances, autosomal dominant inheritance, and juvenile or adulthood disease onset. "Pathogenic variants in SPTLC1, encoding a subunit of serine palmitoyltransferase, cause hereditary sensory and autonomic neuropathy type 1 (HSAN1), and have recently been associated with juvenile ALS." (PMID 39666121, 2024). "Hereditary sensory and autonomic neuropathy type 1 is an autosomal dominant neuropathy caused by the SPTLC1 or SPTLC2 variants." (PMID 38927628, 2024). "Pathogenic variants in SPTLC1 are associated with hereditary sensory and autonomic neuropathy type 1 (HSAN1)." (PMID 39666121, 2024). "Hereditary sensory and autonomic neuropathy type 1 (HSAN1/HSN1) is a peripheral neuropathy most commonly associated with pathogenic variants in the serine palmitoyltransferase complex (SPTLC1, SPTLC2) genes, which are responsible for sphingolipid biosynthesis." (PMID 37107689, 2023). "Alterations of the SPT activity caused by mutations of either SPTLC1 or SPTLC2 gene are linked to neurodegenerative diseases such as hereditary sensory and autonomic neuropathy type I (HSAN1) in human." (PMID 37030501, 2023). "Mutations in SPTLC1 have been associated with hereditary sensory and autonomic neuropathy type I (HSAN-I)." (PMID 32195206, 2019). "Hereditary sensory neuropathy type 1 (HSN-1) is a peripheral neuropathy most frequently caused by mutations in the SPTLC1 or SPTLC2 genes, which code for two subunits of the enzyme serine palmitoyltransferase (SPT)." (PMID 29778900, 2018). "Sptlc1 gene mutations cause a neuropathy known as hereditary sensory neuropathy type I, which might be related with its reported role in the sphingolipid metabolism pathway." (PMID 33260781, 2020). "C-terminal SPTLC1 variants cause peripheral hereditary sensory and autonomic neuropathy type 1 (HSAN1) due to the synthesis of 1-deoxysphingolipids (1-deoxySLs) that form when SPT metabolizes L-alanine instead of L-serine." (PMID 35900868, 2022). "Pathogenic variants in the cytoplasmic domains of SPTLC1 and SPTLC2 can cause hereditary sensory and autonomic neuropathy type 1 (HSAN1) and macular telangiectasia type 2 by abnormally increasing deoxy‐sphingolipid levels." (PMID 38316966, 2024). "Mutations in the SPTLC1 gene are associated with juvenile ALS and Hereditary Sensory and Autonomic Neuropathy type 1 (HSAN1)." (PMID 36143200, 2022). "Mutation in the Sptlc1 gene that encodes one of the SPT subunits, causes the autoimmune disease hereditary sensory neuropathy type 1." (PMID 26431038, 2015). "Hereditary sensory and autonomic neuropathy type I (HSAN1) is an autosomal dominant ulceromutilating neuropathy with variable motor involvement caused by mutations in six genes: SPTLC1, SPTLC2, ATL1, RAB7, DNMT1 and ATL3." (PMID 25567748, 2015).
neuropathy (12 papers, 2015 to 2025). A disorder affecting the nervous system that manifests with pain, tingling, numbness, and/or muscle weakness. "Depending on their location, SPTLC1 variants can therefore be associated with a clinical picture of motor or sensitive neuropathy." (PMID 38927628, 2024). "The neuropathy associated with SPTLC1 mutation exhibited some improvement after supplementation with oral L-serine, which also partially improved the symptoms of sensorimotor and autonomic neuropathy in our PSAT1-related patients." (PMID 36061210, 2022). "HSAN1 neuropathies have been linked to mutations in five different genes, two of which code for SPTLC1 and SPTLC2." (PMID 25947379, 2015). "It was postulated that the phenotypes associated with dominant variants in SPTLC1 may represent a continuum between neuropathy and ALS in some cases, complicated by additional symptoms such as cognitive impairment." (PMID 35627278, 2022). "Furthermore, heterozygous SPTLC1- and SPTLC2-knockout mice exhibit a reduction in SPT activity; however, no neuropathy was documented, again arguing against haplotype insufficiency and for toxic gain of function as the cause of the neuropathology." (PMID 34337561, 2021).
amyotrophic lateral sclerosis (11 papers, 2021 to 2024). Amyotrophic lateral sclerosis (ALS) is a neurodegenerative disease characterized by progressive muscular paralysis reflecting degeneration of motor neurons in the primary motor cortex, corticospinal tracts, brainstem and spinal cord. "Mutations in the coding gene of its first and rate-limiting enzyme, serine palmitoyltransferase long chain base subunit 1 (SPTLC1), cause a childhood-onset form of amyotrophic lateral sclerosis and also a peripheral neuropathy." (PMID 36951944, 2023). "Whereas manifestation of the HSAN1A phenotype was linked to a loss of SPTLC1 function based on the pathogenic variants, recently dominant variants were linked to childhood onset of amyotrophic lateral sclerosis based on a pathological gain of SPTLC1 function." (PMID 35627278, 2022). "Furthermore, we demonstrate that childhood amyotrophic lateral sclerosis (ALS) variants in the SPTLC1 subunit cause impaired ceramide sensing in the SPT-ORMDL3 mutants." (PMID 37308477, 2023). "Causal mutations in SPTLC1 (serine palmitoyltransferase long chain subunit 1) gene within the lipogenic pathway have been identified in amyotrophic lateral sclerosis (ALS), a paralytic and fatal motor neuron disease." (PMID 36345044, 2022). "Pathological SPTLC1 variants cause a form of hereditary sensory and autonomic neuropathy (HSAN1A), and have recently been linked to unrestrained sphingoid base synthesis, causing a monogenic form of amyotrophic lateral sclerosis (ALS)." (PMID 35627278, 2022). "Mutations in the SPTLC1 gene are associated with peripheral neuronal dysfunction including hereditary sensory neuropathy type 1 (HSAN1), childhood amyotrophic lateral sclerosis (ALS) and macular telengectasia type-2." (PMID 36197001, 2022).
hereditary sensory and autonomic neuropathy (7 papers, 2011 to 2026). An instance of sensory peripheral neuropathy that is caused by an inherited modification of the individual's genome. "A total of 75 patients with CMT (including 21 with hereditary sensory neuropathy due to mutations in SPTLC1 and SPTLC2) and 67 healthy controls were enrolled into the study." (PMID 29321234, 2018). "Hereditary sensory neuropathy due to mutations in SPTLC1 was disproportionately represented in this study as samples were collected from patients recruited into a natural history study of HSN1 that was running concurrently." (PMID 29321234, 2018). "For example, hereditary sensory and autonomic neuropathy (HSAN) type 1A is caused by mutations in the serine palmitoyl transferase gene (SPTLC1), which alter the protein's amino acid substrate specificity so that the mutant produces two neurotoxic atypical deoxysphingoid bases." (PMID 22144914, 2011). "Proven disorders include a defect in serine palmitoyltransferase long chain subunit 1 (SPTLC1), which catalyzes the first step in sphingolipid biosynthesis leading to downstream ceramide and sphingolipids biosynthesis, which is associated with hereditary sensory and autonomic neuropathy (HSAN1)." (PMID 24103911, 2013). "Our studies indicate that SPTLC2 variant [c.778G>A, p.Glu260Lys] acts distinctly from hereditary sensory and autonomic neuropathy (HSAN)-causing SPTLC2 variants by causing excess canonical sphingolipid biosynthesis, similar to the recently reported SPTLC1 ALS associated pathogenic variants." (PMID 38041679, 2024).
Sensory neuropathy (7 papers, 2010 to 2024). Peripheral neuropathy affecting the sensory nerves. "Moreover, juvenile ALS due to genetic mutations in SETX and SPTLC1 seems to be associated with an increased propensity to develop sensory neuropathies and dysautonomia." (PMID 37610446, 2023). "SPTLC1 and SPTLC2 variants have been linked to HSAN1; one SPTLC3 variant has also been associated with sensory neuropathy." (PMID 38927628, 2024).
diabetes mellitus (6 papers, 2010 to 2025). A metabolic disorder characterized by abnormally high blood sugar levels due to diminished production of insulin or insulin resistance/desensitization. "Levels of SPTLC1 protein also tend (adjusted p-value, 0.118) to be decreased in islets from subjects with diabetes versus controls." (PMID 40463068, 2025). "In islets from patients with glucose intolerance or with diabetes secondary to pancreatic disease, SPTLC1 and SPTLC2 expression was not different from normogluco-tolerant patients." (PMID 40463068, 2025).
motor neuron disease (5 papers, 2021 to 2024). "In conclusion, our data broaden the phenotype associated with variants in SPTLC1 to include juvenile ALS and implicate sphingolipid metabolism as a pathway in motor neuron disease." (PMID 34459874, 2021). "Interestingly, a study conducted in 2021 proposed the association of variants in serine palmitoyltransferase, long-chain base subunit 1 (SPTLC1) with juvenile ALS (namely ALS4), but not with adult-onset ALS, and implicated sphingolipid metabolism as a pathway in motor neuron disease." (PMID 38802624, 2024).
Obesity (4 papers, 2020 to 2022). Accumulation of substantial excess body fat. "Obesity induced by HFD resulted in increased expression of SPTLC1 (+34.4%, p < 0.05) compared to the control rats." (PMID 34684414, 2021).
type 2 diabetes (4 papers, 2017 to 2025). "Moreover, SPTLC2 mRNA tended to be lower, and SPTLC1 mRNA was significantly decreased, in islets from human subjects with type 2 diabetes versus normoglycemic individuals." (PMID 40463068, 2025).
cognitive decline (3 papers, 2024). "Cognitive decline is an infrequent feature of SPTLC1-associated ALS, which has been described in only one previously reported case." (PMID 39666121, 2024). "Notably, and in contrast with SPTLC1-associated ALS patients, progressive cognitive decline was notable in two patients (P2 and P3), and one patient (P1) had speech delay and autistic features suggestive of a broader neurodegenerative process." (PMID 38041679, 2024).
Cognitive impairment (2 papers, 2021 to 2022). Abnormal cognition is characterized by deficits in thinking, reasoning, or remembering. "It was postulated that phenotypes associated with dominant variants in SPTLC1 may represent a continuum between sensory neuropathy and ALS, complicated by additional symptoms such as cognitive impairment and retina pathology." (PMID 35627278, 2022).
juvenile ALS (2 papers, 2021 to 2024). "De novo variants in the SPTLC1 gene are associated with juvenile ALS, a fatal neurological disorder." (PMID 34459874, 2021).
retinal disease (2 papers, 2021 to 2022). "Interestingly, GO-term based analysis of our proteomic findings obtained in immortalized lymphoblastoid cells displayed retina homeostasis as an affected (up-regulated) biological process and, in 2019, retinal disease was reported in patients carrying SPTLC1 variants." (PMID 35627278, 2022).
Sensorimotor neuropathy (2 papers, 2022 to 2023). "The p.S331Y SPTLC1 variant identified in juvenile ALS has been previously reported as an atypical HSAN1 variant with a distinct mixed sensorimotor neuropathy phenotype." (PMID 36345044, 2022).
Adult onset (1 paper, 2021). Onset of disease manifestations in adulthood, defined here as at the age of 16 years or later. "Having established that variants in SPTLC1 are associated with juvenile ALS, we explored the role of variation in this gene in the pathogenesis of adult-onset ALS by evaluating the occurrence of SPTLC1 variants in a series of 6258 patients with adult-onset ALS." (PMID 34459874, 2021). "Gene burden testing was not significant for SPTLC1 variants as a cause of adult-onset ALS (87 variants in population samples; uncorrected 1-sided Fisher test P value using TRAPD software package = 1.9 × 10−4; not significant after correction for multiple testing of 20 000 genes)." (PMID 34459874, 2021).
Ataxia (1 paper, 2020). Ataxia refers to impaired coordination of voluntary muscle movement. "More specifically, the PIK3R1 gene was under-expressed in neuronal datasets as well as in fibroblasts and peripheral blood, while AKT2, PPP2R5C, and SPTLC1 were found over-expressed in neuronal and fibroblast datasets of the “ataxia” phenotype." (PMID 32937819, 2020).
axonal sensory neuropathy (1 paper, 2023). "Finally, Johnson reported the case of an 11 years old female with ALS carrying SPTLC1 p.Ser331Tyr mutation, who later developed an axonal sensory neuropathy." (PMID 37610446, 2023).
clear cell renal cell carcinoma (1 paper, 2020). "In a clear cell renal cell carcinoma (ccRCC) study, bioinformatics analysis revealed that 10 genes, including SPTSSA, significantly coregulated ccRCC with SPTLC1, and the low expression of SPTLC1 was significantly correlated with the disease progression and poor prognosis of ccRCC." (PMID 33042807, 2020).
cocaine addiction (1 paper, 2025). "We next investigated the effect of Sptlc1 knockdown on dendritic remodeling in cocaine addiction." (PMID 41378204, 2025).
colorectal cancer (1 paper, 2024). A primary or metastatic malignant neoplasm that affects the colon or rectum. "In colorectal cancer, the low expression of SPTLC1 leads to worse prognosis; in renal cell carcinoma, it inhibits cell proliferation, and in lymphoma patients, a mutation of SPTLC1 increases enzymatic activity, thereby sensitizing BCR-ABL tumors to imatinib." (PMID 38927057, 2024).
Ewing sarcoma (1 paper, 2020). A small round cell tumor that lacks morphologic, immunohistochemical, and electron microscopic evidence of neuroectodermal differentiation. "In addition, silencing of either FASN, SCD or SPTLC1 markedly reduced cell proliferation of Ewing sarcoma, further corroborating this conclusion." (PMID 33080033, 2020). "Importantly, silencing of SPTLC1 reduced both colony growth and cell proliferation of Ewing sarcoma cells." (PMID 33080033, 2020). "These lipid metabolism processes are required for cell survival of Ewing sarcoma, as evidenced by the cytotoxicity of their inhibitors (Orlistat against FASN and Myriocin against SPTLC1)." (PMID 33080033, 2020).
Failure to thrive (1 paper, 2021). Failure to thrive (FTT) refers to a child whose physical growth is substantially below the norm. "In this family-based genetic study, exome sequencing was performed in 3 patients diagnosed with juvenile ALS and failure to thrive; this identified de novo variants in SPTLC1 (p.Ala20Ser in 2 patients and p.Ser331Tyr in 1 patient)." (PMID 34459874, 2021). "De novo variants in SPTLC1 (p.Ala20Ser in 2 patients and p.Ser331Tyr in 1 patient) were identified in 3 unrelated patients diagnosed with juvenile ALS and failure to thrive." (PMID 34459874, 2021).
Farber Disease (1 paper, 2023). "The SPTLC1- and SPTSSA-associated disorders represent the former case, while Farber Disease (deficiency of ceramidase encoded by ASAH1) corresponds to an example of the latter case." (PMID 36875645, 2023).
Flegel disease (1 paper, 2025). "This disruption contributes directly to the formation of compact orthohyperkeratosis and parakeratosis seen in Flegel disease, providing a mechanistic link between SPTLC1 dysfunction and clinical lesion development." (PMID 41458780, 2025).
glioma (1 paper, 2015). A benign or malignant brain and spinal cord tumor that arises from glial cells (astrocytes, oligodendrocytes, ependymal cells).